RNU1-136P (RNA, U1 small nuclear 136, pseudogene)
Gene: Small nuclear RNA gene on chromosome 6 (53,219,261 to 53,219,424, forward strand). Ensembl gene ENSG00000206908.
Homologues: Orthologues: chimpanzee U1 (98% identical), macaque U1 (91% identical), rat U1 (86% identical), rabbit U1 (85% identical). Paralogues in human: RNVU1-7 (91% identical), RNU1-1 (90% identical), RNU1-2 (90% identical), RNU1-27P (90% identical), RNU1-28P (90% identical), RNU1-3 (90% identical), RNU1-4 (90% identical), RNVU1-18 (90% identical), RNVU1-29 (90% identical), U1 (90% identical), RNVU1-28 (90% identical), RNU1-67P (89% identical), and 133 more.